DND1P1 (DND microRNA-mediated repression inhibitor 1 pseudogene 1)
Gene: Transcribed processed pseudogene on chromosome 17 (45,585,871 to 45,586,929, forward strand). Ensembl gene ENSG00000264070.
Diseases named in the same sentence as DND1P1 in open-access papers:
DND1P1 is named in the same sentence as 2 diseases in open-access papers, as found by Europe PMC text mining. Sharing a sentence is not in itself a finding about the gene and the disease. The quoted sentences say what the papers report.
Anxiety (1 paper, 2021). Intense feelings of nervousness, tension, or panic often arise in response to interpersonal stresses. "It is noteworthy that 10 genes (KANSL1-AS1, CRHR1, CRHR1-IT1, SPPL2C, RP11-707O23.5, RP11-259G18.1, MAPT-AS1, LRRC37A4P, PLEKHM1, and DND1P1) showed TWS in both datasets (i.e., PsychENCODE and GTEx), implying these genes are promising candidate genes for anxiety." (PMID 34650599, 2021).
DND1P1 also shares sentences with these, for which no sentence is quoted: cancer (1 paper).